ALB (albumin)
Diseases named in the same sentence as ALB in open-access papers (continued):
Sharing a sentence is not in itself a finding about the gene and the disease.
diabetes (continued). "There are few data on albumin-corrected serum anion gap (ACAG) status and mortality in the diabetes." (PMID 39574951, 2024). "Patients with high CAR showed an older age and a higher incidence of diabetes and had higher levels of LDL, white blood cell count, neutrophil count, CRP level in contrast as well as lower HDL cholesterol and albumin levels." (PMID 38673005, 2024). "The interaction effect of OH/ECW for all the patients was statistically significant even after adjusting for age, sex, diabetes prevalence, LVMI, LVEF, cDBP, cPP, and serum albumin levels (P = 0.015)." (PMID 38177252, 2024). "The top 10 predictors of HCC in terms of predictive importance or contribution included age, diabetes, AST, BMI, ALT, INR, race and ethnicity, albumin, total bilirubin, and sex." (PMID 38990573, 2024). "DKD is defined as a chronic kidney disease (CKD) attributable to diabetes and characterized by an estimated glomerular filtration rate (eGFR) < 60 mL/min/1.73 m2 or a urinary albumin-to-creatinine ratio (UACR) ≥ 30 mg albumin/g creatinine." (PMID 39434906, 2024). "Clinical trials, such as the Liraglutide Effect and Action in Diabetes: Evaluation of Cardiovascular Outcome Results (LEADER) study and SUSTAIN-6, have shown that liraglutide and semaglutide can reduce urinary albumin excretion and protect kidney function." (PMID 39597006, 2024). "After adjusting for age, sex, hypertension, diabetes, NIHSS, BMI, and medications, the odds of lower albumin and higher WBC for poor CC compared to good CC were 0.86 (95% CI, 0.79–0.94) and 1.18 (95% CI, 1.04–1.35), respectively." (PMID 38788021, 2024). "Creatinine emerged as the most influential feature, followed by PO2, sepsis, BUN, lactate, ALB, UO, SpO2, WBC, TBIL, RDW, AST, diabetes, DBP, chloride, HR, glucose, BE, platelets, and UTI." (PMID 37789305, 2023). "As expected, patients with HMOD-HRC were older, had had hypertension for a longer time, with more having diabetes, in addition to a lower GFR and higher albumin–creatinine ratio." (PMID 37504556, 2023). "The results showed that PIV was significantly associated with all-cause mortality in patients undergoing PD, after subgroups of patients based on their sex, age, diabetes history, CVD history, CRP level, albumin level, and eGFR (all p < 0.05)." (PMID 36632816, 2023). "Age, vascular access, serum albumin, phosphate, CRP, diabetes, congestive heart failure, and malignancy were independent predictors of all-cause mortality in intention-to-treat analyses (model chi-squared: 250, P < 0.001)." (PMID 38106580, 2023). "The 14 independent variables of significance were as follows: post‐PCI AMR ≥ 250, age, sex, BMI, diabetes, hypertension, hyperlipidemia, stroke, HbA1c, BNP, albumin, troponin I detection peak, random blood glucose levels, and LVEF." (PMID 37997762, 2023). "The RAGE ligands, AGEs, are constantly found in the circulation including HbA1c, fructosamine albumin and CML, all of which are well known to be elevated in diabetes." (PMID 37558746, 2023). "The screened predictors included NLR, ALB, UA, hsCRP, and diabetes mellitus (DM)." (PMID 37790129, 2023). "Similarly, there were several independent readmission risk factors unique to those with a secondary discharge diagnosis of diabetes: discharge against medical advice, discharge home with nursing care, pancreatitis, abnormal serum sodium, urgent or emergent admission, and low serum albumin." (PMID 36835810, 2023). "To investigate the correlation between differential metabolites and diabetes phenotype, we conducted Spearman correlation analysis to examine their relationship with liver functional indicators (ALT, AST, TP, and ALB)." (PMID 37509732, 2023). "BMI: body mass index; DM: diabetes mellitus; DR: diabetic retinopathy; eGFR: estimated glomerular filtration rate; HbA1c: glycated hemoglobin; T2DM: type 2 diabetes mellitus; UAE: urinary albumin excretion." (PMID 37418683, 2023).
diabetes (continued). "Five potential predictors of PDAP after PD catheterization were screened using LASSO regression analysis, including neutrophil-to-lymphocyte ratio (NLR), serum ALBumin (ALB), uric acid (UA), high sensitivity C-reactive protein (hsCRP), and diabetes mellitus (DM)." (PMID 37790129, 2023). "Compared with patients without DR, patients with NPDR and PDR were older; had lower BMI, lower serum albumin levels, and lower eGFR; were accompanied with higher systolic blood pressure (SBP); and had longer duration of diabetes." (PMID 38020197, 2023). "The following parameters were compared: age (57 vs. 57.2 years), female (37.8% vs. 32.6%), diabetes (28.0% vs. 27.9%), serum creatinine (1.0 vs. 1.1), INR (1.42 vs. 1.5), albumin (3.1 vs. 3.1), sodium (137 vs. 135), and MELD (17 vs 15.2)." (PMID 36984593, 2023). "Nevertheless, in patients with CKD and diabetes, OSAS seems to be a factor that results in a higher urinary albumin–creatinine ratio and a lower estimated glomerular filtration rate." (PMID 37366660, 2023). "Instances of interactions between these substances in humans include glycated hemoglobin (HbA1c) and glycated albumin (ALB-g) for EGP, and pentosidine (PTD) for AGE, which have been identified as potential outcome complication predictors in diabetes." (PMID 37629742, 2023). "The proportion of males, duration of diabetes, years of education, systolic blood pressure (SBP), ALT, BUN, Cr, eGFR, UA, ALB, FIB, TC, HbA1c, LDL-C and GLU were all significantly different between the four subgroups (p < 0.05)." (PMID 37576498, 2023). "The urinary concentration of ANGPTL-4 was positively correlated with age, duration of diabetes, FPG, HbA1c, urea, serum creatinine, urine albumin, and UACR in all three groups." (PMID 37108963, 2023). "The duration of diabetes, age, mean arterial pressure (MAP), HbA1c, FBG, urinary albumin/creatinine ratio (UACR), BCVA, AL, and ACD were significantly different between the DR and the NDR groups (p < 0.05)." (PMID 37090790, 2023). "In the comparison of CHB and CHB with LC groups, diabetes and AST, ALT, GGT, total bilirubin, albumin, platelet, and AsAGP levels were significantly different in the univariate analysis." (PMID 36675640, 2023). "Age and sex were nearly included in all models and other parameters included albumin, total bilirubin, platelets, cirrhosis, liver stiffness measurement, ALT, HBeAg status, diabetes, alcohol abuse, and alpha-fetoprotein." (PMID 37582759, 2023). "The clinical hallmarks of diabetes mellitus and diabetic nephropathy with CKD progression include hyperglycemia, a high glomerular filtration rate, and increased urinary albumin excretion." (PMID 36787192, 2023). "Intracellular water was associated with sarcopenic obesity in chronic HD patients independent of dialysis vintage, age, history of CVD, history of stroke, history of diabetes, usage of L- carnitine, SBP, DBP, haemoglobin, albumin, triglyceride, BMI and CRP." (PMID 37803331, 2023). "In decedents, the mean values of age, waist circumference, HbA1c, diabetes duration, SBP, albumin-to-creatinine ratio, serum creatinine, and eGFR were higher compared to those in patients who were alive." (PMID 38249989, 2023). "Regarding ALB-g, although there is a lack of direct evidence establishing a causal link between elevated levels of ALB-g and compromised bone health, it can be inferred that such an association exists based on its potential as a biomarker for the detection of diabetes mellitus." (PMID 37629742, 2023). "The factors associated with the increased frailty levels in our patients included older age, low BMI, low serum albumin, high CRP, the comorbidity of diabetes and cardiovascular diseases, and the history of fractures, which were consistent with prior studies." (PMID 37696942, 2023).
diabetes (continued). "The results of this study show that diabetes induction increases IR, urine volume, water consumption, GFR, urine glucose, urine albumin, urine urea, and kidney NOX4 and ICAM1 gene expressions in both female and male mice, as well as in the offspring." (PMID 36755074, 2023). "The spot urinary protein to creatinine ratio (PC ratio) and the albumin to creatinine ratio (ACR) have been studied in patients with renal disease, diabetes, and preeclampsia to assess proteinuria." (PMID 37065365, 2023). "Factors tested using multivariate analysis, i.e. age, C-reactive protein, D-dimer, albumin, body temperature, Sequential Organ Failure Assessment (SOFA) score, and diabetes." (PMID 37767018, 2023). "The models included three to seven parameters including age, sex, albumin, total bilirubin, platelets, cirrhosis, liver stiffness measurement, ALT, HBeAg status, diabetes, alcohol abuse, or alpha-fetoprotein." (PMID 37582759, 2023). "Patients with sarcopenia were older than those without sarcopenia, and they had higher SARC-CalF scores, baPWV, blood glucose level, diabetes duration, and VPT but lower ALT level and poorer nutrition status (including albumin, vitamin D, and BMI)." (PMID 36643790, 2023). "The final variables of age, monocytes, neutrophils, serum albumin, serum potassium, history of CVD, history of diabetes, serum creatinine, and HbA1C were selected to participate in the construction of the nomogram." (PMID 38074152, 2023). "Meanwhile, six variables (age, diabetes mellitus, Child–Pugh class B/C, MELD score, albumin, and pentosidine) were revealed as significant factors associated with low gait speed in univariate analysis." (PMID 37780552, 2023). "Participants who alive also had a lower prevalence of diabetes and hypertension, a higher DBP, urinary creatinine, total cholesterol, LDL-C level, a lower SBP, urinary albumin, AST, serum creatinine, serum uric acid and fasting plasma glucose levels." (PMID 37441866, 2023). "Incubation of glycated-albumin demonstrated elevated surface expression of RAGE in healthy PMNs, whereas, in PMNs isolated from those with diabetes showed surface expression of RAGE which correlated with glycemic control." (PMID 36895726, 2023). "Multivariable logistic regression was used to evaluate the influence of 91 SNPs on urine albumin-to-creatinine ratio (UACR)-related traits and kidney damage (any pathology indicating renal injury), stratifying by diabetes." (PMID 37446387, 2023). "Long-term diabetes led to an increased concentration of VEGF-A, TAT, and urinary excretion of total protein and albumin, and a decrease in the concentration of sVCAM-1." (PMID 37834118, 2023). "The relation of peritoneal albumin and protein loss to comorbidity, especially to diabetes mellitus (DM), has not been precisely elucidated." (PMID 37048753, 2023). "The mean BMI of the patients was 25.5 kg/m2, the mean duration of diabetes was 112.4 months, the mean SBP was 141.6 mmHg, the mean serum albumin was 36.9 g/L, and the mean hemoglobin was 125.3 g/L." (PMID 36820611, 2023). "Variables that were associated with mortality in both eras included older recipient and donor age, male sex, encephalopathy, diabetes, higher MELD, higher creatinine, and lower albumin." (PMID 37917059, 2023). "Age, gender, smoking status, BMI, diabetes, hypertension, serum creatinine, serum uric acid, total cholesterol, HDL-C, ALT, AST, waist circumference, TGs, urinary albumin and ACR were significantly different among the VAI tertiles (all P < 0.05)." (PMID 36969806, 2023). "Opposite trends were detected for SBP, DBP, temperature, albumin level, bicarbonate level, glucose level, hematocrit level, hemoglobin level, RBC count, and complicated diabetes." (PMID 37206106, 2023). "The independent risk factors for in‐hospital death included age >65 years old, complication of diabetes, renal impairment on admission (Cr > 73 μmol/L and eGFR < 60 ml/min 1.73 m2), WBC > 9.5 × 109/L and ALB < 35 g/L." (PMID 35591765, 2022).
diabetes (continued). "The glycation of albumin can be sufficient to oxidatively jeopardize adipocyte physiology and increase LDH activity in patients with diabetes." (PMID 36589820, 2022). "There were no major variations across these two cohorts regarding age, sex, ASA classification, diabetes incidence, serum CEA levels, serum CA199 levels, serum hemoglobin, plasma albumin, or NRS 2002 scores." (PMID 35624511, 2022). "Previous evidence suggested that increasing values of long-term BPV predict the development and progression of diabetes organ target lesions, such as nephropathy, including correlation with PWV and urinary albumin excretion, another indicator of kidney lesion." (PMID 35774421, 2022). "These patients were more likely to have diabetes, previous CHF, multivessel disease, low hemoglobin, high albumin, and were more likely to have prescribed peri-procedural medications (RAAS blockers, beta-blockers, CCBs, and diuretics)." (PMID 35572997, 2022). "A significant difference was observed in the PFT, HbA1C, UTP, age, urine creatinine, urine microalbumin, UACR, ALB, urea, SCr, UA, TG, LDL, eGFR, Hb, PT, duration of diabetes mellitus, and hypertension levels among the three DM subgroups (P < 0.05)." (PMID 36507087, 2022). "This association remained stable with an extended adjustment for serum albumin, LDL cholesterol, smoking status, diabetes mellitus, statin use, triglycerides, BMI and systolic and diastolic blood pressure: OR = 0.80, 95% CI 0.72–0.86, p = 0.0000003." (PMID 34914850, 2022). "One study reported urinary mtDNA/creatinine ratio was increased in individuals with diabetes versus NDC, and positively correlated with urinary albumin excretion (r = 0.0242, p < 0.05)." (PMID 36010558, 2022). "For cardiovascular mortality, age, gender, cancer, hypertension, recent physical condition, diabetes, BMI, GHB, and albumin were adjusted." (PMID 35647067, 2022). "Eleven available predictors for 5-year mortality nomogram, including age, sex, diabetes, CVD, BMI, smoking, lipid-lowering drugs, SBP, hemoglobin, albumin and BUN, were identified by logistic regression model." (PMID 35509033, 2022). "Diabetes mellitus was significantly more common in patients with MPC compared to BPC (42.6%(23/54) vs. 23.1%(12/52), p = 0.038), and the serum albumin levels of patients with MPC were significantly lower than those of patients with BPC (p < 0.0001)." (PMID 36333670, 2022). "Patients in the low AFR group were older and had higher rates of hypertension and diabetes as well as high levels of NLR, globulin, and fibrinogen, but lower levels of albumin." (PMID 35572991, 2022). "Patients in the highest quartile (quartile 4) tended to be older, suffered more from diabetes, were more likely to have higher BMI, TC, TG, LDL-C, and hypersensitive C-reactive protein (hs-CRP) levels but lower serum albumin and HDL-C levels." (PMID 35399692, 2022). "After adjustment for time-dependent age and dialysis vintage, gender, diabetes, TAWG, and serum albumin, patients with hyponatremia based on TASNa had a higher risk of new MACE (HR 2.33; 95% CI 1.16–4.68; model 3) compared to those with normonatremia." (PMID 35780279, 2022). "Patients with higher mCI values were more likely to be younger, with lower prevalence rates of diabetes mellitus, higher BUN, SCr, albumin, nPNA, and lower hs-CRP." (PMID 36254391, 2022). "Correlation of prevalence of fungal infection in diabetic foot ulcer with variables, i.e. age, duration of diabetes mellitus (in years), HbA1c, FBS, PPBS, and albumin." (PMID 35978737, 2022). "Univariate Cox regression analysis indicated that diabetes mellitus, hypertension, phosphate, CCI, BMI, SBP, DBP, MAP, MV, levels of creatinine and albumin, GFR, and APACHE II and SOFA scores correlated with survival time." (PMID 36425293, 2022). "Age, BMI, diabetes, AST, ALT, platelet, and albumin were significantly higher in patients with NFS >0.676 compared to patients with NFS ≤ 0.676." (PMID 35463006, 2022).
diabetes (continued). "Anthropometric parameters such as age, gender, duration of diabetes and biochemical parameters such as fasting blood sugar (FBS), post prandial blood sugar (PPBS), glycated hemoglobin (HbA1c), and albumin were recorded." (PMID 35978737, 2022). "Common predictors used in studies included age, sex, eGFR, urinary albumin to creatinine ratio (ACR), serum creatinine (SCr), diabetes, cardiovascular disease, body mass index (BMI), and high blood pressure." (PMID 35881639, 2022). "BNP correlated significantly with age, hemoglobin, history of CVD, and urinary albumin, whereas urinary albumin correlated significantly with age, sex, systolic blood pressure, hemoglobin, LDL cholesterol, eGFR, diabetes, and BNP." (PMID 37234386, 2022). "We suggest all patients with diabetes have their GFR and urine albumin-to-creatinine ratio (UACR) checked annually." (PMID 35012483, 2022). "A univariable analysis revealed nine variables to be included in the model: random blood glucose, years with diabetes, cardiovascular diseases, peripheral arterial diseases, DFU history, smoking history, albumin, creatinine, and C-reactive protein." (PMID 36472981, 2022). "The difference of age, DBP, BMI, CVAI, duration of diabetes, HbA1c, ALT, AST, GGT, albumin, BUN, triglycerides, TC, high-density lipoprotein cholesterol, LDL-C, statin use and metformin use reached statistical significance between the two groups." (PMID 35979441, 2022). "Blood urea, albumin protein, and creatinine concentrations in diabetic animals (DAC) are higher than in the control group, which is related with diabetes." (PMID 35407153, 2022). "Model 1: age, gender, and race; Model 2: age, gender, race, BMI, diabetes, waist circumference, HDL-cholesterol, glycohemoglobin, AST, ALT, GGT, serum albumin, serum creatinine, and uric acid." (PMID 35991666, 2022). "An earlier in vivo study showed that rats with diabetes and diabetic kidney disease (DKD) fed with a high-fat diet, had increased urine protein and urine albumin levels compared to control rats." (PMID 36012119, 2022). "Urinary albumin excretion was reduced in diabetic ApoE KO mice following treatment with an ACE2 minicircle (Mean ± SEM; Diabetes 48 ± 5 μg/day, Diabetes + minicircle 28 ± 3 μg/day, p = 0.008)." (PMID 35624851, 2022). "LDL: low-density lipoprotein, HDL: high-density lipoprotein, FBG: fasting blood glucose, ACR: albumin/creatinine ratio, eGFR: estimated glomerular filtration rate, BSA: body surface area, BMI: body mass index, T2DM: type 2 diabetes mellitus." (PMID 36337798, 2022). "Variables including gender, age, diabetes mellitus (DM), HBV, HCV, NLR, hemoglobin, albumin, antiviral therapy, liver cirrhosis, and ALBI grade, in addition to tumor size > 6.5 cm, were incorporated into 5 different models." (PMID 36169915, 2022). "The final model included eleven independent predictors: age, sex, diabetes, cardiovascular disease, BMI, smoking, lipid-lowering drugs, SBP, hemoglobin, albumin, and BUN." (PMID 35509033, 2022). "Features, including calcium, alkaline phosphatase (ALP), albumin, urine ketone, urine occult blood, creatinine, alanine aminotransferase (ALT), and diabetes were selected." (PMID 35054370, 2022). "The patients who needed ICU were elderly and had higher frequencies of diabetes, higher basal and peak values of hs-cTnI, LDH, CRP, procalcitonin and D-dimer levels, and also higher ferritin and lower albumin values." (PMID 33501850, 2021). "Higher level of urinary MA, age, CRP, lower level of serum albumin, ABI, eGFR, CLI, diabetes, cerebral infarction, and CHD were related to CVLE, and statin therapy was related to CVLE in Cox univariate analysis (p<0.05)." (PMID 34707745, 2021). "The crude analyses and analyses adjusted for age, albumin, creatinine, history of CVD, and history of diabetes, give similar results." (PMID 33632160, 2021).